NEUROG1 (neurogenin 1)
Diseases named in the same sentence as NEUROG1 in open-access papers:
NEUROG1 is named in the same sentence as 38 diseases in open-access papers, as found by Europe PMC text mining. Sharing a sentence is not in itself a finding about the gene and the disease. The quoted sentences say what the papers report.
colorectal cancer (15 papers, 2007 to 2025). A primary or metastatic malignant neoplasm that affects the colon or rectum. "Methylation analysis of NEUROG1 in CRC tumors showed progressive hypermethylation associated with neoplastic development, from normal mucosa–hyperplastic polyp–adenoma–primary carcinoma, and finally metastatic colorectal carcinoma, showing the highest methylation." (PMID 32605302, 2020). "In the distal colorectal cancer network, two biomarkers were hubs including NEUROG1 methylation (degree centrality = 0.15) and RUNX3 methylation (degree centrality = 0.15)." (PMID 28623901, 2017). "Concurrent promoter methylation in NEUROG1 and CDKN2A (p16) was associated with poor DFS in stages II and III colorectal cancer patients, and CHFR promoter methylation indicated poor prognosis in stage II colorectal cancer patients." (PMID 26157509, 2015). "We have recently reported that concurrent methylation in NEUROG1 and CDKN2A (p16) is associated with higher recurrence in colorectal cancer patients whereas CIMP classification based on the number of methylated markers was not." (PMID 26157509, 2015). "In this study, CIMP-high did not have a prognostic role; however, concurrent methylation in NEUROG1 and CDKN2A (p16) was independently associated with poor survival in colorectal cancer patients treated with adjuvant FOLFOX." (PMID 26157509, 2015). "However, the FB-high cases presented hypermethylation especially in the type C genes, including MINT2 and 31, P16 and NEUROG1, these methylation have been reported in the colorectal cancers with methylation phenotype." (PMID 28977914, 2017). "Although the functional role of promoter methylation in NEUROG1 and CDKN2A (p16) is inconclusive, CDKN2A (p16) promoter methylation was associated with poor survival in stages II and III colorectal cancer patients who received adjuvant fluoropyrimidine-based chemotherapy." (PMID 26157509, 2015). "Moreover NEUROG1 has been described to be frequently hypermethylated in colorectal cancers and has been proposed as a marker to classify the CpG-island methylator phenotype in colorectal cancers." (PMID 24708595, 2014). "We obtained 401 colorectal cancer specimens and successfully quantified DNA methylation in eight CIMP-specific gene promoters (CACNA1G, CDKN2A, CRABP1, IGF2, MLH1, NEUROG1, RUNX3, and SOCS1) using MethyLight technology." (PMID 31690257, 2019). "Notably, several genes such as ALX4, CHD5, MYOD1, NEUROG1, and RASSF5, whose methylation profile distinguishes this group of HCC patients from the other HCC patients, were previously reported to be similarly hypermethylated and associated with poor prognosis in colorectal cancer." (PMID 25093504, 2014). "The Laird methylation marker panel used to determine CIMP status of colorectal cancers consists of the CACNA1G, IGF2, NEUROG1, RUNX3 and SOCS1 genes." (PMID 20846368, 2010). "We obtained 920 colorectal cancer specimens and quantified DNA methylation in the 8 CIMP-specific gene promoters (CACNA1G, CDKN2A, CRABP1, IGF2, MLH1, NEUROG1, RUNX3 and SOCS1) by MethyLight technology." (PMID 17474983, 2007). "Although NEUROG1 and CDKN2A have shown to be methylated in colorectal cancers, CSMD1-3 methylation did not correlate with NEUROG1 (p = 0.432, R = .1081) or CDKN2A (p = 0.537, R = .08488) methylation, though these two markers did positively correlate with each other (p<0.01)." (PMID 23505554, 2013). "Utilizing MethyLight technology (real-time PCR), we quantified DNA methylation in 8 CIMP-specific promoters {CACNA1G, CDKN2A (p16), CRABP1, IGF2, MLH1, NEUROG1, RUNX3 and SOCS1} in 758 non-MSI-high colorectal cancers obtained from two large prospective cohorts." (PMID 17474983, 2007).
adenoma (4 papers, 2015 to 2025). A neoplasm arising from the epithelium. "In the first pathway, adenoma formation occurs in an MMR-proficient background, and carcinogenesis is characterized by APC and/or KRAS mutation and IGF2, NEUROG1, CDK2A, and/or CRABP1 hypermethylation." (PMID 34201893, 2021). "This increase in NEUROG1 methylation from normal colonic mucosa to hyperplastic polyps, also progressing in adenomas, primary adenocarcinomas and metastatic adenocarcinomas, was previously evidenced in tissue." (PMID 32605302, 2020). "Moreover, MMR-deficient adenomas with a high grade of dysplasia revealed hypermethylation in four other genes, IGF2, CRABP1, NEUROG1, and CDKN2A." (PMID 34201893, 2021). "In our study, we demonstrate that serum NEUROG1 methylation could be a useful test for the detection of premalignant advanced adenomas and cancer, for the screening of CRC in asymptomatic individuals." (PMID 32605302, 2020). "In a detailed analysis according to the characteristics of adenomas, we found that individuals with adenomas sized ≥10 mm and with villous component registered elevated methylated NEUROG1 in contrast to small and tubular adenomas (Mann–Whitney tests, p-values < 0.001)." (PMID 32605302, 2020). "DNA was available for eight such adenomas, and 3/8, 4/8, 6/8, and 2/8 revealed hypermethylation of IGF2, NEUROG1, SFRP1, and SFRP2, respectively." (PMID 26203307, 2015). "Moreover, Maki-Nevala and colleagues found higher methylation levels in four CIMP marker genes, namely NEUROG1, CDKN2A, IGF2, and CRABP1, in MMR-proficient adenomas compared to normal mucosa." (PMID 34201893, 2021). "Individuals with no colorectal findings and benign pathologies showed low serum NEUROG1 methylation, similar to non-advanced adenomas." (PMID 32605302, 2020). "Notably, the difference was significant already in adenomas with low-grade dysplasia (89 % vs. 21 %, p < 0.001, for IGF2 and 56 % vs. 8 %, p < 0.001, for NEUROG1)." (PMID 26203307, 2015). "The prospective LS series revealed increased methylation in adenomas and carcinomas vs. normal colonic mucosa for the CIMP markers IGF2, NEUROG1, and CRABP1 (p values mostly non-significant due to small numbers of specimens)." (PMID 26203307, 2015).
glioblastoma (4 papers, 2013 to 2025). The most malignant astrocytic tumor (WHO grade IV). "Indeed, the nucleosome just upstream of the NEUROG1 was absent in RA treated H9 cells and in glioblastoma 248 cells which express NEUROG1, suggesting that the NDR right upstream of TSS is important for gene expression." (PMID 23637628, 2013).
medulloblastoma (4 papers, 2014 to 2024). A malignant, invasive embryonal neoplasm arising from the cerebellum. "NEUROG1 is a known signature gene within the RL-svz (rhombic lip subventricular zone), playing a foundational role in the formation of Group 4 medulloblastoma (MB)." (PMID 39160595, 2024). "CDK8 stands out as a top dependency, similar to OTX2, Neurog1, and Neurod1, well-established genes that sustain stemness and drive proliferation in medulloblastoma 34–37." (PMID 39574899, 2024). "The rest 29 antigens were all expressed by TAAs and NEUROG1 and IMPG2 were expressed by over 90% tumors, making them the most suitable antigen targets for Group 3 medulloblastoma." (PMID 39160595, 2024).
schizophrenia (4 papers, 2012 to 2022). A major psychotic disorder characterized by abnormalities in the perception or expression of reality. "Among patients with schizophrenia, patients with Neurog1 polymorphism showed decreased verbal memory, language ability, and visuospatial abilities." (PMID 36430421, 2022). "In neuropsychiatric disorders, for example, polymorphisms within the Neurog1 regulatory region are associated with language deficits, and Chr 5q31 containing the Neurog1 locus is also associated with schizophrenia." (PMID 36430421, 2022). "Genetic variants in the 5q region have previously been found to be associated with schizophrenia (e.g., IL3, IL4, IL9, NEUROG1)." (PMID 22723893, 2012). "Although Neurog1 polymorphism is not the cause of schizophrenia, this polymorphism is more severe in patients with schizophrenia." (PMID 36430421, 2022).
colon cancer (3 papers, 2011 to 2017). "Highly connected biomarkers (with degree centrality) were BRAF mutation (0.19) and methylation-related markers including CDKN2A (0.17), IGF2 (0.17), RUNX3 (0.17), CACNA1G (0.15), CRABP1 (0.15), and NEUROG1 (0.15) in the proximal colon cancer network." (PMID 28623901, 2017). "In total, 31 CpG sites, located in 8 different genes (RUNX3, MLH1, NEUROG1, CDKN2A, IGF2, CRABP1, SOCS1 and CACNA1G) were investigated in 64 distinct colon cancers and 2 colon cancer cell lines." (PMID 24466191, 2014).
colorectal tumors (3 papers, 2013 to 2020). "On the other hand, the evaluation of NEUROG1 in other non-colorectal tumors and benign gastrointestinal pathologies would also be of utility to estimate the specificity of the biomarker." (PMID 32605302, 2020). "Finally, we performed methylation-specific PCR on 76 colorectal tumors to determine DNA methylation status for CSMD1 and known methylation targets ALX4, RUNX3, NEUROG1, and CDKN2A." (PMID 23505554, 2013).
autism (2 papers, 2007 to 2023). Persistent deficits in social interaction and communication and interaction as well as a markedly restricted repertoire of activity and interest as well as repetitive patterns of behavior. "This article reports the fourth family across the globe consisting of two children (siblings) with a similar phenotype together with autism involving a likely pathogenic variant in the NEUROG1 gene." (PMID 36647078, 2023). "This is the fourth and a novel report of a sibling pair harboring a homozygous variant in the NEUROG1 gene with autism as an additional phenotype." (PMID 36647078, 2023). "This is also the first report to present autism as an additional phenotype being associated with the NEUROG1 gene." (PMID 36647078, 2023). "We provide a hypothetical framework which could explain the pleiotropic effect of a dysfunctional NEUROG1 protein leading to autism and posit it as a candidate for diagnosis of autism spectrum disorder with congenital cranial dysinnervation disorder." (PMID 36647078, 2023). "Using single point association analyses and haplotype analyses, we found significant evidence for an association of autism with PITX1 but not with H2AFY or NEUROG1." (PMID 18053270, 2007).
deafness (2 papers, 2013 to 2018). An inherited or acquired condition characterized by the complete loss of the ability to hear from one or both ears. "The deafness of Neurog1 KI mice is likely caused by a structurally disorganized cochlea and variably differentiated hair cell stereocilia." (PMID 29321651, 2018). "The congenital palsy of cranial nerves V (causing the severe gulp and mouth motor disorder) and VIII (causing the deafness) represents a congenital cranial dysinnervation disorder or Moebius syndrome variant and we suggest NEUROG1 as the likely causative gene in this boy." (PMID 23419067, 2013). "The human NEUROG1 resides within the DFNB60 locus for non-syndromic autosomal recessive deafness on chromosome 5q22-q31, but linkage data have excluded it from being causative in the DFNB60 patients." (PMID 23419067, 2013).
hyperplastic polyp (2 papers, 2015 to 2020). A polyp found mainly in the stomach and colon. "In relation to the colorectal findings groups, 0.00% (0.00–0.00%) median and IQR methylation of NEUROG1 resulted in individuals with no colorectal findings and all the benign pathology sub-groups (inflammatory and hyperplastic polyps, hemorrhoids, diverticula and other benign pathologies)." (PMID 32605302, 2020).
liver cancer (1 paper, 2017). An epithelial or non-epithelial malignant neoplasm that arises from the liver. "In the comparison between the liver cancer and the other cancer groups, cDMCs (FDR < 0.0001) were detected at the promoters of the SPARC, NEUROG1, SH3GL3, and ITGA4 genes." (PMID 28751909, 2017).
lung carcinoma (1 paper, 2013). "Of the 30 common Significant DNA methylated genes across Stages II and III, GRIK2 and NEUROG1 have been previously reported being DNA methylated biomarker for lung squamous cell carcinoma, and a Stage I biomarker in lung cancer respectively." (PMID 24369052, 2013).
neuroblastoma (1 paper, 2015). Neuroblastoma (NB) is the most common solid, extracranial childhood tumor. "Mapping the upstream regulator networks that drive DE genes in highly MNA cells compared with MYCN single copy cells elucidated several central nodes not previously linked to MNA neuroblastoma (e.g. HRAS, MAPK1, RAF1, NEUROG1 and ER)." (PMID 26673823, 2015).
prostate carcinoma (1 paper, 2023). A carcinoma that arises from epithelial cells of the prostate gland. "Neurog1, a basic helix-loop-helix protein, would affect neuronal differentiation and more importantly, the highly methylated Neurog1 would be disturbed in prostate cancer and thus be chosen as one of the cancer methylation markers." (PMID 37191432, 2023). "In the study of human LNCaP prostate cancer cells, curcumin could demethylate the Neurog1 promoter and reactivate its mRNA and protein expression, which indicated that curcumin may be promising in epigenetic therapy of prostate cancers." (PMID 37191432, 2023).
rectal cancer (1 paper, 2019). A primary or metastatic malignant neoplasm that affects the rectum. "In 2012, Jo and colleagues used methylation specific PCR to examine a panel of 5 CIMP markers (i.e., CACNA1G, IGF2, NEUROG1, RUNX3, and SOCS1) in rectal cancer patients receiving 5-FU-based neoadjuvant chemoradiation." (PMID 31390840, 2019).
rhabdoid tumor (1 paper, 2024). An aggressive malignant embryonal neoplasm usually occurring during childhood. "Interestingly, both NEUROG1 and NEUROD2 were hypermethylated and down-regulated in AT/RTs when compared to MBs in our DM-DE gene analysis and they harbor DMRs, which were hypermethylated in AT/RTs compared with PSCs and bound by BRD9 in rhabdoid tumors." (PMID 38499326, 2024).
tumor (16 papers, 2010 to 2024). "For NEUROG1 methylation, fruit consumption was associated with tumor methylation at a cut point of 40% (OR = 0.27, 95% CI 0.08, 0.94) for AA, while for EA, higher fruit consumption was associated with greater odds of a high methylation tumor at methylation cut points of 15–35%." (PMID 29930328, 2018). "Particularly, immunotherapies targeting neoantigens from oncogenic driver mutations such as CTNNB1, DDX3X, and SMARCA4 and TAAs which have possible implications in tumor progression such as NEUROG1 and PIK3R3 are attractive for a better outcome in patients." (PMID 39160595, 2024). "NR2E1 and NEUROG1 had significantly higher levels of methylation in cortical tumours relative to infratentorial and midline tumours (P ≤ 0.05)." (PMID 28388012, 2018). "We found significantly higher methylation in the transcription start site of NEUROG1 in cortical tumours when compared with both midline and infratentorial tumours." (PMID 28388012, 2018). "It was consistent that oncogenic miR-21 and miR-155 involved in the progression and invasion of GBM, and a set of their common key targets such as LHX6, DRD1, NEUROG1 and RAB27B were also associated with tumor progression." (PMID 29312626, 2017). "The frequencies of hypermethylation for IGF2 and NEUROG1 were significantly increased in all tumor types when compared to normal colon." (PMID 26203307, 2015). "This is consistent with earlier analyses revealing methylation of NEUROG1 in primary tissue not to be associated with tumor stage (A.P. and F.K., data not published)." (PMID 24708595, 2014). "Interestingly, some of these genes have been previously associated with CIMP in other tumor types, such as p73, GSTP1, SOCS-1, CACNA1G, CRABP1, NEUROG1 and RUNX3." (PMID 20830311, 2010). "Infratentorial tumours also had significantly lower levels of methylation in NR2E1 and NEUROG1 when compared to midline tumours (P ≤ 0.01)." (PMID 28388012, 2018). "While there is no consensus on a gene panel to determine the CIMP status of a tumour, one of the most commonly used is the Weisenberger panel of genes comprising of CACNA1G, NEUROG1, RUNX3, SOCS1 and IGF2." (PMID 28351398, 2017). "NEUROG1 is a transcription factor involved in neuronal development and differentiation, and CDKN2A (p16) is a tumor suppressor that inhibits cyclin-dependent kinases CDK4 and CDK6." (PMID 26157509, 2015). "For NEUROG1, on the other hand, hypermethylation in serum was detectable independently of LDH levels and tumor stage." (PMID 24708595, 2014). "Regarding CRC, increased NEUROG1 methylation was also evidenced, with statistically significant differences when compared to no colorectal findings group and no neoplasia (Mann–Whitney tests, p-value = 0.026 and p-value = 0.011, respectively)." (PMID 32605302, 2020). "Specific hypermethylation of NEUROG1 and NR2E1 was identified as a feature of cortical tumours." (PMID 28388012, 2018). "To compare the CIMP classifications derived from our clustering analysis to those derived from the Weisenberger panel of genes, we analysed the methylation status of our tumour samples using MethyLight at each gene from this panel (CACNA1G, NEUROG1, SOCS1, IGF2, RUNX3)." (PMID 28351398, 2017). "Other clinico-pathological factors, including tumor location, did not affect the prognostic role of concurrent methylation in NEUROG1 and CDKN2A (p16)." (PMID 26157509, 2015).
cancer (10 papers, 2014 to 2024). A tumor composed of atypical neoplastic, often pleomorphic cells that invade other tissues. "In our study we demonstrate that serum NEUROG1 methylation could be useful for the detection of AA and cancer." (PMID 32605302, 2020). "For example, our data demonstrate that miR-21 and miR-155 are related with progression and invasion of GBM by regulating marker genes of cancer metastasis, such as LHX6, DRD1, NEUROG1 and RAB27B, and thereby contributing to GBM patient survival." (PMID 29312626, 2017). "However, we also detected EZH2 binding sites in AT/RT-unique DMRs in DE genes such as NEUROG1 and TCEA3, which are shown to be down-regulated in cancer and are relevant for early development." (PMID 38499326, 2024). "Therefore, the combination of methylated NEUROG1 and FIT, both non-invasive tests, could be very helpful for the detection of cancers and premalignant AA, to be incorporated into CRC screening programs." (PMID 32605302, 2020).
colorectal (2 papers, 2015 to 2020). "The large, asymptomatic screening cohort analyzed constitutes another strength of our study, allowing the estimation of the diagnostic capability of methylated NEUROG1 in a real-life screening scenario that included a variety of colorectal pathologies." (PMID 32605302, 2020).
NEUROG1 also shares sentences with these, for which no sentence is quoted: adenocarcinoma (2 papers); autism spectrum disorder (2); embryonic carcinoma (2); infection (2); Stroke (2); ankylosing spondylitis (1); autosomal recessive hearing loss (1); hemorrhoid (1); hepatocellular carcinoma (1); Hyperglycemia (1); hyperprolinemia type 2 (1); Kabuki syndrome 2 (1); lung squamous cell carcinoma (1); mental disorder (1); metabolic disease (1); Obesity (1); pyridoxine-dependent epilepsy (1); tubular adenoma (1); Weaver syndrome (1).